ENSG00000238594
Synonyms: LOC124901527
Gene: Small nucleolar RNA gene on chromosome 6 (150,164,584 to 150,164,686, forward strand). Ensembl gene ENSG00000238594.
Gene Ontology:
Biological process: RNA processing
Cellular component: nucleolus
Homologues: Paralogues in human: SNORD13 (89% identical), SNORD13P1 (88% identical), SNORD13P3 (88% identical), SNORD13D (86% identical), SNORD13E (85% identical).